PIK3CA (phosphatidylinositol-4,5-bisphosphate 3-kinase catalytic subunit alpha)
Diseases named in the same sentence as PIK3CA in open-access papers (continued):
Sharing a sentence is not in itself a finding about the gene and the disease.
tumor (continued). "The proportion of patients with high pAKT activity was similar in tumours harbouring pathogenic alterations of any member of the PIK3CA pathway compared to wild-type tumours (79% versus 77%, respectively; p > 0.05)." (PMID 39322687, 2024). "Inavolisib (GDC-0077) is a novel PI3Kα inhibitor and offers high selectivity and specificity, effectively inhibiting tumor growth driven by PIK3CA mutations while minimizing the inhibition of wild-type PI3K, thereby reducing side effects." (PMID 39769140, 2024). "Molecular analyses have identified PIK3CA mutations in RGNTs, suggesting that these mutations promote tumor growth and survival by activating the PI3K/AKT signaling pathway." (PMID 39457636, 2024). "As expected, PIK3CA mutations were amongst the most frequently detected pathogenic variants with 33.9% of all tumours and 43.5% of HR+/HER2- MBCs harbouring oncogenic alterations of this key signalling hub." (PMID 39322687, 2024). "In a phase 1 study, taselisib treatment was associated with markable tumor-suppressing effects in patients with PIK3CA-mutated metastatic BC." (PMID 38255807, 2024). "Metastatic BC patients with PIK3CA-mutated HR-positive/HER2-negative tumours exhibit a poor prognosis and hormone resistance." (PMID 39197004, 2024). "The distribution of PIK3CA mutations was heterogeneous between coupled samples, being gained from primary tumour to BM in one patient and lost in other four cases." (PMID 38347094, 2024). "In contrast to ESR1 mutations, which are mostly acquired following prior endocrine treatment, PIK3CA mutations are found at similar frequencies in primary and metastatic breast tumors, and are generally considered an early event related to tumor initiation." (PMID 38605020, 2024). "Mutations in PIK3CA are associated with increased activation of the Akt pathway, tumor growth, and invasiveness, with the overexpression of PIK3CA being associated with poorer patient outcomes." (PMID 38596668, 2024). "Several tumors harboring genomic alterations with FDA-approved indications in other tumor types were found including pathogenic PIK3CA, EGFR Exon 19/20 insertions, KRAS G12C (N = 1), FGFR fusions (N = 1), BRAF V600E mutations (N = 4), and BRCA2 (N = 1)." (PMID 39191445, 2024). "Since PIK3CA mutations have also been reported in this tumor subtype, PI3K inhibitors can also be an effective therapeutic alternative." (PMID 39130753, 2024). "Another important consideration includes the presence of multiple PIK3CA mutations prior to treatment, as 27% of ECs harbor more than one PIK3CA mutations, a feature more common in EC than any other tumor type." (PMID 38920692, 2024). "Unfortunately, these authors only analyzed the clinicopathological meaning of PIK3CA amplification, which was found to be associated with tumor stage and grade in this investigation." (PMID 38616230, 2024). "Taselisib inhibits tumor cell proliferation and induces apoptosis by potently and selectively inhibiting p110α, particularly in the context of activating PIK3CA mutation." (PMID 36900211, 2023). "The change was bi-directional, more commonly observed from PIK3CA mutated to wild-type status (14.9%, 95% CI 11.8–18.2; n tumor pairs = 453) rather than the opposite direction (8.9%, 95% CI 6.1–12.1; n tumor pairs = 943)." (PMID 37392328, 2023). "Using tumor whole-exome sequencing, PIK3CA was identified to be the most frequently mutated gene in HNSCC overall, with a subset of HPV-associated tumors having PIK3CA or PIK3R1 as the only mutated cancer gene." (PMID 37686653, 2023). "Among the 1200 patients who underwent tumor exome analysis, we found a total of 141 patients (representing 11.75% of the screened population) with PIK3CA or PIK3R1 somatic mutation." (PMID 36934165, 2023).
tumor (continued). "Activating mutations of PIK3CA are correlated with poor prognosis, even in patients whose tumor is wholly excised." (PMID 37509254, 2023). "In 30%–40% of HR+/HER2– BC patients, activating mutations were found in the PIK3CA gene, making it one of the most commonly altered genes in this type of tumor." (PMID 38148576, 2023). "Aspirin has shown potential efficacy in prolonging survival of a subset of colorectcal cancer patients, especially those with tumor PIK3CA mutation." (PMID 37538192, 2023). "The highest frequency of mutations detected was in the KRAS gene, in tumor biopsies and plasma samples, followed by mutations of the PIK3CA, NRAS and BRAF genes." (PMID 37176143, 2023). "The detection of PIK3CA mutations in archival or fresh tumor tissue and plasma-derived circulating tumor DNA (ctDNA) is dependent on analytical and methodological factors, thus possibly affecting clinical validity and utility." (PMID 37392328, 2023). "As cells are able to proliferate through more mechanisms, the pressure selection for tumor cells harboring an activating PIK3CA mutation, for instance H1047R as seen in our data, would possibly be lower in the obese setting." (PMID 37479706, 2023). "In the NAC group, tumor with PIK3CA mutations showed significantly poorer response than tumor with PIK3CA wild-type (response rates 10.5% vs. 34.1%, p = 0.03)." (PMID 37106324, 2023). "HPV-positive OPC has the highest number of PIK3CA mutations compared with other HPV-negative tumours." (PMID 37559138, 2023). "From 2012 to 2015, comparisons of PIK3CA mutation detection in tumor tissue and plasma revealed a concordance of only 27.5% to 72.5%." (PMID 38001722, 2023). "PIK3CA mutations are usually considered to be closely related to advanced tumor stage and poor survival." (PMID 37370046, 2023). "Cancer is a common abnormality in PROS, and it is possible that metastatic forms of tumor cells with activating mutations in PIK3CA or MAP3K3 can invade tissue/vasculature, circulate in the blood, and reside in microvascular lesions, including CCMs." (PMID 37109059, 2023). "Among the oncogenes, MUC16 (mutated in 18.9% of tumours), PIK3CA (12.4%), and KRAS (11.1%) were the most frequently mutated across the profiled samples." (PMID 37550388, 2023). "In line with this, evidence that dependence on PI3K p110β isoform is of clinical relevance has also emerged from the analysis of multiple tumor biopsies from a patient with PIK3CA-mutated metastatic breast cancer, enrolled in a human study of alpelisib." (PMID 37596643, 2023). "For example, the PIK3CA gene is mutated in 16% of primary TNBCs and mutations in PIK3CA reduce the dependency of tumor cells on growth factors, promoting cell growth and transformation." (PMID 36769287, 2023). "HS‐10352 is a novel selective PI3Kα inhibitor showing inhibitory effects on the proliferation of cancer tumor cell lines harboring PIK3CA mutations." (PMID 38037839, 2023). "Different PIK3CA mutations activating through unique mechanisms is supported by the discovery of tumours harbouring double PIK3CA mutations in cis, with these tumours showing enhanced sensitivity to PI3K inhibition." (PMID 36635288, 2023). "Patients with an HR+/HER2−, PIK3CA wt tumor appeared to have shorter mOS, 18.9 months (CI 14.1–25.1), compared to patients with a tumor harboring any PIK3CA mutation (23.4 months; CI 17.0–27.6)." (PMID 37178424, 2023). "By contrast, patient ST2267, who had a baseline PIK3CA H1047R tumor mutation, experienced primary resistance to futibatinib." (PMID 37377403, 2023). "Specifically, only FGFR3 mutation had been already detected in primary tumor tissues, while PIK3CA was acquired in 28% of cases." (PMID 37064137, 2023).
tumor (continued). "DNA sequencing confirmed that these organoids harbored mutations in CRC genes (APC, KRAS, and PIK3CA) that corresponded to the mutations found in the original tumor." (PMID 37085135, 2023). "Our results reveal various evidence for the involvement of immune-related pathways in luminal tumors harboring ARID1A and PIK3CA mutations, as well as a unique Tumor-infiltrated immune cells composition." (PMID 38017109, 2023). "Even lower alpelisib concentrations (10 ng/ml and 100 ng/ml) combined with low-dose metronomic VRL led to a significant reduction of cell viability of PIK3CA-mutated cells, and the anti-tumor activity was comparable with the effects at 1000 ng/ml alpelisib." (PMID 36998707, 2023). "Further, we performed a sequencing analysis on CTCs isolated from the EDF of two patients whose primary tumour displayed a mutation in the PIK3CA gene—either H1047R or H1047L—with a variant allele frequency of 28% or 30%, respectively." (PMID 36823365, 2023). "Our results suggested that in patients with PIK3CA mutation identified by liquid biopsy, the variant AF of PIK3CA strongly correlated with tumor burden." (PMID 37344660, 2023). "Reported almost two decades ago, PTEN mutations in canine HSA can occur in 4% (2/47) to 10% (2/20) of cases and appear to play an important role in regulating PIK3CA, a more frequently mutated gene in this tumor." (PMID 37368773, 2023). "For example, in the tumors from T16-046, a PIK3CA coding mutation was detected with variable allele frequencies across tumor deposits collected at primary presentation and relapse, with apparent positive selection in relapse." (PMID 37220750, 2023). "TMB was similar between PIK3CA-wild type and PIK3CA-mutated tumours in the entire cohort and within each MKS/ERS subgroup." (PMID 37935787, 2023). "We also detected the E545G PIK3CA mutation in one PDX model that responded to DIACC3010 monotherapy with tumor stasis." (PMID 37749105, 2023). "The most common genomic alterations leading to a recommendation were high tumor mutational burden TMBhigh (17.2%) and activating alterations in PIK3CA (13.8%) and ERBB2 (10.3%)." (PMID 37062035, 2023). "In this study, patients with PIK3CA wt tumor had a shorter mOS than patients having PIK3CA-mutated aBC." (PMID 37178424, 2023). "The therascreen® PIK3CA RGQ PCR Kit diagnostic test, (QIAGEN Manchester, Ltd.), has also been approved to detect patients with PIK3CA mutations, which can be performed either on tumour tissue samples and/or in circulating tumour DNA (ctDNA) in plasma." (PMID 37542343, 2023). "In the NAC group, tumor with PIK3CA mutations showed significantly poorer response than tumor with PIK3CA wild-type (p = 0.03)." (PMID 37106324, 2023). "The TCGA also highlighted a gene mutational spectrum for HPV-related tumours, including PIK3CA, DDX3X, CYLD and FGFR." (PMID 36980527, 2023). "The PFS benefit was significant in patients with PIK3CA-mutated tumors, suggesting a pathway to further personalize treatment to tumor biology." (PMID 36980743, 2023).
tumor (continued). "This detection platform was used to quantify ctDNA, and to analyze the methylation and tumor characteristic mutations of the PIK3CA gene in clinical samples." (PMID 39188296, 2023). "Pik3a is an oncogenic mutation of pan-cancer species, and the pathogenic mutation of PIK3CA leads to uncontrolled proliferation of cells and eventually tumor formation." (PMID 36765522, 2023). "PI3K is especially highly expressed in HCC tumor tissue, and the upregulation of PIK3CA was associated with HCC proliferation and negatively correlated with apoptosis." (PMID 36768977, 2023). "We also found MTOR gene mutations in four tumours and an uncommon PIK3CA gene mutation in one tumour in this study." (PMID 36816543, 2023). "VeM-associated metastatic tumor cells or VeM-Endothelial cells (VeM-ECs) carrying activating PIK3CA mutations are invasive." (PMID 37109059, 2023). "Incorporating our findings that PIK3CA mutation portends a worse prognosis even when tumor burden is low, patients should consider specific PIK3CA inhibitor in the earliest time after failure of standard first-line treatment of ET plus a CDK4/6 inhibitor." (PMID 37344660, 2023). "The most frequently mutated gene overall was PIK3CA (39%), with a significantly higher mutation rate in MKSlo/ERShi tumours compared to the three other MKS/ERS subgroups (52% vs 32–33%, p = 6.47 × 10−5)." (PMID 37935787, 2023). "They used a semi-conductor based NGS method and found discordant PIK3CA mutation status between primary tumor and metastasis in 4 cases, with loss of mutation in the metastatic lesion in three cases." (PMID 36943861, 2023). "Of note, the patient with 40–100% tumor viability had an FBXW7 mutation (as well as mutations in PIK3CA and KMT2D)." (PMID 37568706, 2023). "Further, one case of MSI status was detected in a HER2-negative, ISH unamplified, HR-positive tumor bearing a PIK3CA gene mutation (c.1624G > A, p.(Glu542Lys))." (PMID 38137385, 2023). "The PDX mouse models have demonstrated that human VeM-ECs with different activating PIK3CA mutations behave like tumor cells and invade mouse tissue to form lesions with human VeM-ECs, similar to VeM phenotypes in humans." (PMID 37109059, 2023). "PIK3CA mutations are particularly common in tumours with low-grade and early-stage endometrioid histology." (PMID 37175518, 2023). "Since both PIK3CA and ErbB2 alterations reflect major driver events in tumor development, these results suggest that high RNA-protein correlations are associated with tumor functionality in the case of gene amplification." (PMID 37290530, 2023). "Pik3caH1047R conditional mammary knock-in promotes de novo tumor formation with long latency and incomplete penetrance, suggesting PIK3CA mutations are weakly oncogenic in isolation." (PMID 37471270, 2023). "Here, we present the course of diagnosis and treatment of a patient with advanced SqCLC, harboring not only CDKN2A mutation but also PIK3CA amplification, Tumor Mutational Burden-High (>10 mutations/megabase), and a Tumor Proportion Score of 80%." (PMID 36835617, 2023). "While most mis-sense oncogenic mutations discovered in tumours are at hot-spot locations (E542K, E545K and H1047R), more than 25% of all mutations in PIK3CA occur outside the hotspots." (PMID 36635288, 2023). "The proinflammatory cytokine interleukin 6 (IL-6) was overexpressed in OCCC with concurrent ARID1A deletion and PIK3CA mutation, and the cytokine promoted tumour cell growth and survival." (PMID 38275587, 2023).
tumor (continued). "Additional analysis from BELLE-2 and BELLE-3 trials using the BEAMing PCR assay showed a similar concordance of PIK3CA mutation status between circulating tumor (ct)DNA and tumor tissue analysis (77% and 83%, respectively)." (PMID 36672617, 2023). "Of the limited descriptive studies to date in familial breast cancer, when compared with sporadic tumours, there is a markedly reduced frequency of somatic PIK3CA mutations in BRCA1/2mut tumours (5–16%)." (PMID 36831687, 2023). "In view of the high prevalence of PIK3CA mutations in all cancers, it remains critical to explore the role of PI3Kα inhibitors in a wider variety of tumor types." (PMID 36385120, 2022). "Thirty-eight out of forty-seven patients were evaluated, and PIK3CA variants were identified in 21% of tumor samples: overall, one mutation was detected in exon 4 (2.6%), two in exon 9 (5.3%) and four in exon 20 (10.5%)." (PMID 35740668, 2022). "Due to the small numbers, only a trend was observed indicating that patients with wildtype tumours achieved pCR more often than patients with PIK3CA-mutations." (PMID 36279023, 2022). "The panel-targeted sequencing results of tumor specimens revealed high incidences of oncogenic PIK3CA and DNMT3A mutations in patients aged ≥65 years, which highlighted the impact of age-dependent genomic alterations on CRC tumorigenesis." (PMID 35203549, 2022). "Targeted NGS for PIK3CA mutational testing on FFPE tumor and metastasis samples from patients with HR+/HER2− metastatic breast cancers is a reliable and robust diagnostic strategy." (PMID 36428975, 2022). "Abnormal activation of the PI3K/AKT signaling pathway confers proliferative advantages to tumor cells, and PIK3CA mutations are one of the most common types of CRC." (PMID 36135759, 2022). "Concomitant driver mutations included activating mutations in classic oncogenes (e.g., KRAS, NRAS, EGFR, and PIK3CA), as well as loss-of-function mutations in tumor suppressors (e.g., BRCA1/2 and PTEN)." (PMID 36369474, 2022). "One missense mutation (p.R38H) in PIK3CA was identified in both peritoneal fluid ctDNA and tumor gDNA in EC1 patient, and another missense mutation (p.R38C) in PIK3CA was identified in both the peritoneal fluid and plasma ctDNA of EC4." (PMID 35626111, 2022). "The PIK3CA mutation indicated that the tumor were susceptible to BYL719 but resistant to endocrine therapy." (PMID 36046364, 2022). "Primary objectives were the prevalence of somatic PIK3CA-mutations and their association to tumour characteristics." (PMID 36279023, 2022). "In conclusion, CYH33 exhibits a manageable safety profile and preliminary anti-tumor efficacy in solid tumors harboring PIK3CA mutations." (PMID 36385120, 2022). "The tumor sample was also analyzed for genomic mutations, in which the mutation p.542/545 (E542K-E545K/Q) in exon 9 of the PIK3CA gene was identified." (PMID 36010260, 2022). "The present study identified concomitant genomic alterations in all tumor samples carrying PIK3CA mutations." (PMID 35778737, 2022). "The PIK3CA mutation frequency among HPV-positive tumours was reported to be approximately half of that found in HPV-negative cancers." (PMID 35267596, 2022). "Overall, the mutational analysis of PIK3CA status in primary tumor and metastasis samples by RT-PCR showed a low concordance rate of 33.3%." (PMID 36428975, 2022). "The exploratory outcome was the relationship between the efficacy of CYH33 treatment and tumor biomarker status, including PIK3CA mutations." (PMID 36385120, 2022). "In Section 3.5, we observed that somatic point mutations of PTEN and PIK3CA were scarce in high-CIN tumours." (PMID 35326573, 2022).